PLXDC1 (plexin domain containing 1)
Description:
Plays a critical role in endothelial cell capillary morphogenesis.
Synonyms: TEM3; TEM7
Tractability: Antibody: UniProt places it where antibodies can reach, with high confidence; UniProt predicts a signal peptide or a membrane-spanning region; its Gene Ontology location is reachable by antibodies, with medium confidence. PROTAC: ubiquitination databases record sites on it.
Gene: Protein-coding gene on chromosome 17 (39,063,313 to 39,154,394, reverse strand). Ensembl gene ENSG00000161381.
Subcellular location: Secreted; Cell membrane (Isoform 1); Cell junction, tight junction; Secreted (Isoform 2); Secreted (Isoform 3); Cytoplasm (Isoform 4)
Gene Ontology:
Molecular function: protein binding
Biological process: angiogenesis; spinal cord development
Cellular component: extracellular region; receptor complex; bicellular tight junction; cytoplasm; dendrite; neuronal cell body; plasma membrane
Genetic constraint (gnomAD): Loss-of-function variants: 28 observed, 44.42 expected, observed/expected ratio (o/e) 0.63, 90% interval 0.47 to 0.86. The upper end of that interval is the gene's LOEUF score, 0.86, which puts it in group 3 of 6, group 1 being the genes least tolerant of losing a copy. Missense variants: 549 observed, 619.07 expected, observed/expected ratio (o/e) 0.89, 90% interval 0.83 to 0.95. Synonymous variants: 202 observed, 235.68 expected, observed/expected ratio (o/e) 0.86, 90% interval 0.76 to 0.96.
Homologues: Orthologues: chimpanzee PLXDC1 (99% identical), macaque PLXDC1 (97% identical), dog PLXDC1 (90% identical), pig PLXDC1 (89% identical), rat Plxdc1 (82% identical), mouse Plxdc1 (81% identical), rabbit PLXDC1 (81% identical), guinea pig PLXDC1 (81% identical), tropical clawed frog plxdc1 (58% identical), zebrafish plxdc1 (44% identical), Drosophila melanogaster l(1)G0289 (32% identical), Caenorhabditis elegans pxd-1 (30% identical). Paralogues in human: PLXDC2 (50% identical).
Diseases named in the same sentence as PLXDC1 in open-access papers:
PLXDC1 is named in the same sentence as 20 diseases in open-access papers, as found by Europe PMC text mining. Sharing a sentence is not in itself a finding about the gene and the disease. The quoted sentences say what the papers report.
colorectal cancer (4 papers, 2016 to 2023). A primary or metastatic malignant neoplasm that affects the colon or rectum. "TEM7, also termed PLXDC1, has been used as a prognostic marker for resectable gastric and colorectal cancers." (PMID 26891329, 2016).
epithelial ovarian cancer (4 papers, 2013 to 2023). "PLXDC1 (angiogenic marker gene) siRNA-incorporated chitosan NP coated with HA (HA-CH-NP/siRNA, size of 200 nm) reduced the tumour growth in epithelial ovarian cancer with ~ 2.1-fold increased binding of NP on cancer cells with significant reduction of PLXDC1 expression." (PMID 38112935, 2023). "Therefore, we considered PLXDC1 to be a valid target for ovarian cancer therapy." (PMID 29890852, 2018).
gastric cancer (3 papers, 2021 to 2024). A primary or metastatic malignant neoplasm involving the stomach. "Abnormalities in PLXDC1 have been reported to be closely associated with tumor disease, and PLXDC1 has been demonstrated to be a biomarker for immune evasion and a poor prognosis in gastric cancer." (PMID 37529244, 2023). "Upregulated PLXDC1 in various tumors, for example, gastric cancer and glioblastoma, has a poor survival outcome." (PMID 39060620, 2024). "PLXDC1 increases invasion in gastric cancer, and TCIRG1 is an osteoclast-specific vacuolar proton pump subunit that acts as a metastasis enhancer in hepatocellular carcinoma." (PMID 33420367, 2021).
colorectal tumor (2 papers, 2011 to 2016). "In the human, mouse and chick Plxdc2 has one related gene, Plxdc1, which was isolated in a screen for genes upregulated in human colorectal tumour endothelium (and originally named tumour endothelial marker 7, TEM7." (PMID 21283688, 2011).
diabetic retinopathy (2 papers, 2014 to 2017). "PLXDC1 was also found to be highly expressed in the endothelial cells of another human disease- diabetic retinopathy- and is highly specific to diseased blood vessels." (PMID 25535841, 2014). "In diabetic retinopathy 34 genes including AP15, GRB2, IL17A, PLXDC1, C5 and L1CAM were studied in a single year in which, C5 and L1CAM are reported as recently as in 2016." (PMID 28761062, 2017).
Osteogenic Sarcoma (2 papers, 2016 to 2021). "Plxdc1 is involved in endothelial cell capillary morphogenesis and diseases such as Osteogenic Sarcoma and Mulchandani–Bhoj–Conlin Syndrome." (PMID 34884814, 2021).
Burkitt lymphoma (1 paper, 2024). A rare form of malignant mature B-cell non-Hodgkin lymphoma. "MMP19 was highly expressed in adipocytes, heart, liver, and Burkitt’s lymphoma cells (Raji cells), and PLXDC1 was highly expressed in CD4+ T cells, CD56+ NK cells, CD8+ T cells, thymus cells and pineal cells." (PMID 39118664, 2024).
melanoma (1 paper, 2024). A malignant, usually aggressive tumor composed of atypical, neoplastic melanocytes. "MMP19 was strongly associated with melanoma (r = 0.593, p = 0.012), while PLXDC1 was associated with Leishmania infection (r = 0.581, p = 0.014) and ribosomes (r = −0.517, p = 0.033)." (PMID 39118664, 2024).
Sepsis (1 paper, 2022). Sepsis is defined as life-threatening organ dysfunction caused by a dysregulated host response to infection. "Given the role of PLXDC1 endothelial regulation, further investigation in sepsis is warranted with particular focus on alveolar-capillary unit." (PMID 36572854, 2022).
tumor (25 papers, 2011 to 2025). "In pancreatic ductal adenocarcinoma (PDAC), PLXDC1+ tumor-associated pancreatic stellate cells (TPSCs) are located adjacent to LRRC15+ myCAFs and SPP1+ macrophages, collectively forming a desmoplastic and immunosuppressive perimeter that promotes CD8+ TEX." (PMID 41425545, 2025). "Genes overexpressed in tumor-associated macrophages compared to normal adrenal macrophages included PLXDC1 and PLAU (log2FC > 0.5, BH adj." (PMID 36271074, 2022). "The genes encoding PLXDC1 are highly expressed during tumor angiogenesis and enriched in many types of tumor endothelial cells, including glioblastoma endothelium, ovarian cancer, gastric cancer, renal cell carcinoma, colorectal cancer, lung cancer, breast cancer, and osteosarcoma." (PMID 37139333, 2023). "Whereas, vascular endothelium growth factor (VEGF) and CD31 (a tumor neovasculature protein) were highly expressed in both normal and tumor tissues, PLXDC1 was specifically expressed in tumor-associated endothelial cells in tumor tissues compared with normal tissues." (PMID 29890852, 2018). "The PLXDC1+ TPSC‐related spatial niche around the tumor boundary acted as a barrier to T cells, and PLXDC1+ TPSCs interacted with T cells via immune checkpoint receptors, thereby promoting T cell exhaustion." (PMID 40091495, 2025). "To further investigate the relationship between PLXDC1+ TPSC‐associated immunosuppressive niche and the exclusion of T cells around the tumor boundary, we analyzed interactions between PLXDC1+ TPSCs and CD8 Tex cells." (PMID 40091495, 2025). "Mapping cell abundance of different PSC subclusters revealed PLXDC1+ TPSCs predominantly located in neighboring clusters 1 and 2, enriched at the tumor edge." (PMID 40091495, 2025). "Despite the comprehensive multi‐omics approach and the novel insights into PLXDC1+ PSCs in the tumor microenvironment, our study has several limitations." (PMID 40091495, 2025). "Plexin domain-containing 1 (PLXDC1), also known as tumor endothelial marker 7, is a member of the tumor vascular endothelial marker family." (PMID 37139333, 2023). "PLXDC1 is significantly expressed in tumor endothelial cells and has been demonstrated to be involved in tumor angiogenesis." (PMID 37529244, 2023). "With few reports on the role or mechanism of PEDF and PLXDC in DR or neovascular fundus diseases, PLXDC1 has been shown to inhibit cell proliferation and invasion in tumor cells, promote endothelial cell separation in mice." (PMID 37139333, 2023). "The protein PLXDC1 (Plexin Domain Containing 1) was first discovered to be significantly expressed in the endothelium of human tumor vessels." (PMID 37529244, 2023). "The closest homolog to Plxdc2, Plxdc1 was initially identified as overexpressed in blood vessels of solid human tumors, resulting in the original terminology tumor endothelial marker 7 (TEM7, Plxdc1) and tumor endothelial marker 7 related (TEM7R, Plxdc2)." (PMID 33657166, 2021). "This infiltrative shift occurs mostly along perivascular spaces and relies on the over-expression of PLXDC1 (Plexin Domain Containing 1) by tumor cells and on the restoration of the endothelial component of blood brain barrier." (PMID 33513872, 2021). "PLXDC1’s tumor blood vessel expression was found in a wide range of cancer types, including liver cancer, breast cancer, ovarian cancer, pancreatic cancer, colorectal cancer, lung cancer, neuroblastoma and sarcomas." (PMID 35201465, 2021). "Particles were loaded with siRNA against PLXDC1 (siPLXDC1), which is involved in the promotion of cell migration and invasion of tumor endothelial cells (see also Section 4.2)." (PMID 31652539, 2019). "Using the HA–CH–siPLXDC1 particles (150 mg/kg, IV twice per week), the authors showed a significant decrease in the level of PLXDC1 mRNA in the tumor mass compared to CH–control siRNA and CH–siPLXDC1." (PMID 31652539, 2019).
tumor (continued). "PLXDC1, a cell surface transmembrane protein, is overexpressed in tumor endothelial cells, which can contribute to tumor angiogenesis, metastasis, migration, and invasion." (PMID 29890852, 2018). "PLXDC1 silencing by the HA-CH-NP/siRNA significantly inhibited tumor growth in A2780 tumor-bearing mice compared with that in the control group (p < .01), and mRNA expression of PLXDC1 was significantly reduced in the HA-CH-NP/siRNA-treated group." (PMID 29890852, 2018). "A similar effect on PLXDC1 expression, proliferation, and apoptosis was confirmed in the HeyA8 tissues compared to A2780 tumor tissues." (PMID 29890852, 2018). "In this study, we demonstrated that the HA-labeled CH-NPs incorporating PLXDC1 siRNA (HA-CH-NP/PLXDC1 siRNA) can be used for targeted siRNA delivery to the tumor vasculature." (PMID 29890852, 2018). "To determine the potential biological effects of HA-CH-NP/mPLXDC1 siRNA treatment in tumor tissues, we stained the tumors for markers of PLXDC1, cell proliferation (Ki67), microvessel density (MVD, CD31), and apoptosis (TUNEL)." (PMID 29890852, 2018). "To determine the biological effects of PLXDC1 in tumor endothelial cells, we assessed migration, invasion, and tube formation after PLXDC1 silencing." (PMID 29890852, 2018). "We focused on silencing the angiogenic gene PLXDC1 as an important factor for anti-angiogenesis tumor therapy." (PMID 29890852, 2018). "Based on these results, we selected PLXDC1 as a potential therapeutic target in anti-angiogenesis tumor therapy." (PMID 29890852, 2018). "PLXDC1 (also called tumor endothelial marker 7) was discovered as one of the genes enriched in many types of human tumor endothelial cells." (PMID 25535841, 2014). "Plxdc1 is upregulated in the stromal endothelial cells of various tumours and has been shown to be upregulated and essential during endothelial cell capillary morphogenesis." (PMID 21283688, 2011). "Our findings suggested that PLXDC1+ TPSC–related niche around the tumor boundary may exclude T cell infiltration and promote the exhaustion of its neighboring T cells." (PMID 40091495, 2025). "It further identifies PLXDC1+ PSCs near aggressive LRRC15+ cancer‐associated myofibroblasts and SPP1+ macrophages, forming a desmoplastic and immunosuppressive tumor niche that promotes CD8+ T cell exhaustion, contributing to poor immunotherapy outcomes in pancreatic cancer." (PMID 40091495, 2025). "Combined with our results, PLXDC1 could not only be a biomarker for poor outcomes but also for tumor anti-angiogenesis." (PMID 39060620, 2024). "Although it was initially identified as a marker for tumor endothelial cells, subsequent research has shown that PLXDC1 plays important roles in both normal physiological and pathological conditions, particularly in the dynamic adjustment of the ECM and the regulation of cell behavior." (PMID 39118664, 2024). "Similarly, Plxdc1 was first described in a screen for novel tumor endothelial members and expression of both Plxdc1 and Plxdc2 is elevated in the endothelium of solid tumors." (PMID 33657166, 2021). "We selected PLXDC1, which is overexpressed in tumor endothelial cells, for the present study." (PMID 29890852, 2018). "To target PLXDC1 as an effective therapeutic gene in tumor endothelial cells, we selected siRNA-based treatment strategy that could specifically knock down the target gene and was nontoxic to other sequences, even in normal cells." (PMID 29890852, 2018). "Furthermore, in nine independent PDAC cohorts comprising 1169 samples, we identified PLXDC1+ TPSCs as unfavorable prognostic markers, with six cohorts showing statistical significance, implying their potential involvement in tumor progression." (PMID 40091495, 2025). "Four types of PSCs (CCL19+, ISG15+, PLXDC1+, and MYH11+) were identified as TPSCs with high RO/E scores in tumor tissues, while remained three PSC subclusters were identified as CPSCs, mainly in the control pancreas and persist in tumor tissues." (PMID 40091495, 2025).
tumor (continued). "PLXDC1 is a transmembrane receptor for the pluripotent factor PEDC that has important anti-angiogenic and anti-tumor functions." (PMID 36271074, 2022). "Some studies have also considered the targeting of plexin domain containing 1 (PLXDC1), previously known as TEM7, which is overexpressed in endothelial cells of all four tumor types." (PMID 31652539, 2019). "Notably, PLXDC1+ TPSCs, located near aggressive LRRC15+ myCAFs and SPP1+ macrophages, formed a desmoplastic and immunosuppressive niche around the tumor boundary, promoting CD8 T cell exhaustion." (PMID 40091495, 2025). "This study demonstrated that PLXDC1+ TPSCs could localize closely with basal‐like Mals and SPP1+ macrophages around the tumor boundary to generate a desmoplastic and immune‐suppressive niche." (PMID 40091495, 2025). "PLXDC1/TEM7 was highly enriched in the blood vessels of tumor tissues but not in the blood vessels of adjacent normal tissue." (PMID 35201465, 2021). "Therefore, the endothelial cells in the A2780 tumor tissue expressed CD44, thus providing an attractive tumor model for targeting both PLXDC1 and CD44 in tumor endothelial cells." (PMID 29890852, 2018). "We first determined whether PLXDC1 and CD44 expression in the tumor neovasculature of cancer patients in an effective target." (PMID 29890852, 2018). "Additionally, by dividing ST slides into malignant region, tumor boundary, and nonmalignant region, PLXDC1+ TPSCs were significantly enriched at the tumor boundary." (PMID 40091495, 2025). "Notably, PLXDC1+TPSCs located near aggressive LRRC15+ myCAFs and SPP1+ macrophages could form a desmoplastic and immunosuppressive niche around the tumor boundary, promoting CD8 T cell exhaustion in pancreatic ductal adenoma." (PMID 41425545, 2025). "In contrast to a recent study, despite being the closest homolog of PLXDC2, PLXDC1 was not significantly differentially expressed between tumor samples and normal samples at the gene level, leaving PLXDC2 as the only TEM suitable for predicting the survival outcomes of GC." (PMID 34124056, 2021). "PLXDC1 silencing in the HUVEC cells resulted in significant inhibition of cell migration, invasion, and tube formation compared with the results obtained using the control siRNA, suggesting that PLXDC1 could be an important target for anti-angiogenesis tumor therapy." (PMID 29890852, 2018). "The A2780 cells did not express PLXDC1 or CD44, whereas the tumor endothelial cells showed high expression of CD44." (PMID 29890852, 2018).
cancer (9 papers, 2015 to 2025). A tumor composed of atypical neoplastic, often pleomorphic cells that invade other tissues. "CPSCs differentiated into CCL19+ TPSCs in immune‐enriched regions, MYH11+ TPSCs in the stromal region, and PLXDC1+ TPSCs, which exhibited cancer‐associated myofibroblasts (myCAFs) phenotype linked to poor prognosis." (PMID 40091495, 2025). "Plxdc1 expression has been described as prognostic marker and modulating factor for various human cancers." (PMID 33657166, 2021). "A collation of 73 TEC marker genes from five studies showed that at most, only two cancer types shared one of these five genes (EGFL6, HEYL, MMP9, SPARC, PLXDC1), and the rest were expressed uniquely in only one cancer." (PMID 32375250, 2020). "Several reports from other cancers showed that patients with high GLUD1, ANXA4, and PLXDC1 expression have low overall survival, but our findings in CCA are contrasting." (PMID 33193605, 2020).
infection (2 papers, 2021 to 2023). The state of being infected such as from the introduction of a foreign agent such as serum, vaccine, antigenic substance or organism. "Preincubation of RRV with soluble Plxdc2 decoy receptor reduced infection by ~60%, while overexpression of Plxdc1 and 2 dramatically enhanced RRV susceptibility and cell-cell fusion of otherwise marginally permissive Raji cells." (PMID 33657166, 2021). "At a minimum, our data on RRV-YFP ΔgL infection of Plxdc1 and Plxdc2 overexpressing Raji cells confirms that RRV can efficiently use Plxdc1 and Plxdc2 as entry receptors in the absence of gL." (PMID 33657166, 2021). "Even though the effect of Plxdc1/2 overexpression on RRV-YFP ΔgL infection was slightly less pronounced than the effect on RRV-YFP wt and RRV-YFP gH-AELAAN infection, this data demonstrates that the use of Plxdc1 and Plxdc2 as RRV 26–95 entry receptors is possible in a gL-independent manner." (PMID 33657166, 2021). "Therefore, changes in susceptibility to infection mediated by Plxdc1/2 overexpression should be readily detectable and allow for a clear differentiation of the contribution of Plxdc1/2 to RRV infection over the very low intrinsic susceptibility to infection." (PMID 33657166, 2021). "We therefore aimed to analyze if infection with a RRV 26–95 gL deletion mutant (RRV-YFP ΔgL) is influenced by Plxdc1 and 2 expression to a similar degree as RRV-YFP wt and RRV-YFP gH-AELAAN infection." (PMID 33657166, 2021). "RRV 26–95 infection was enhanced by both Plxcd1 and Plxdc2 expression and similarly RRV 26–95 gH/gL or gH alone facilitated fusion with Plxdc1 or Plxdc2 overexpressing Raji cells." (PMID 33657166, 2021). "RRV-YFP wt infection increased from 0.14 ± 0.04% on empty vector transduced Raji cells to ~8.5% upon EphA7 overexpression and to ~17% upon Plxdc1/2 overexpression, without pronounced differences between the Plxdc family members." (PMID 33657166, 2021). "Furthermore, deletion of the Eph-interaction motif in RRV-YFP gH-AELAAN did not impact the infection of Plxdc1/2 overexpressing cells in comparison to RRV-YFP wt infection." (PMID 33657166, 2021).
PLXDC1 also shares sentences with these, for which no sentence is quoted: glioblastoma (2 papers); ovarian cancer (2); proliferative diabetic retinopathy (2); colon carcinoma (1); glioma (1); hepatocellular carcinoma (1); malignant glioma (1); sarcoma (1).